CYP4F11 (cytochrome P450 family 4 subfamily F member 11)
Description:
A cytochrome P450 monooxygenase involved in the metabolism of various endogenous substrates, including fatty acids and their oxygenated derivatives (oxylipins). Mechanistically, uses molecular oxygen inserting one oxygen atom into a substrate, and reducing the second into a water molecule, with two electrons provided by NADPH via cytochrome P450 reductase (CPR; NADPH-ferrihemoprotein reductase). Catalyzes with high efficiency the oxidation of the terminal carbon (omega-oxidation) of 3-hydroxy fatty acids, such as 3-hydroxyhexadecanoic and 3-hydroxyoctadecanoic acids, likely participating in the biosynthesis of long-chain 3-hydroxydicarboxylic acids. Omega-hydroxylates and inactivates phylloquinone (vitamin K1), and menaquinone-4 (MK-4, a form of vitamin K2), both acting as cofactors in blood coagulation. Metabolizes with low efficiciency fatty acids, including (5Z,8Z,11Z,14Z)-eicosatetraenoic acid (arachidonate) and its oxygenated metabolite 8-hydroxyeicosatetraenoic acid (8-HETE). Catalyzes N- and O-demethylation of drugs such as erythromycin, benzphetamine, ethylmorphine, chlorpromazine, imipramine and verapamil. Catalyzes the oxidation of dialkylresorcinol 2.
Synonyms: CYPIVF11
Tractability: Small molecule: it belongs to a druggable protein family. Antibody: UniProt predicts a signal peptide or a membrane-spanning region. PROTAC: ubiquitination databases record sites on it; its protein half-life has been measured; a small molecule that binds it is known.
Target class: Enzyme; Oxidoreductase
Gene: Protein-coding gene on chromosome 19 (15,912,367 to 15,934,933, reverse strand). Ensembl gene ENSG00000171903.
Subcellular location: Endoplasmic reticulum membrane; Microsome membrane
Pathways (Reactome):
Metabolism: Eicosanoids; Fatty acids; Miscellaneous substrates; Synthesis of Leukotrienes (LT) and Eoxins (EX)
Gene Ontology:
Molecular function: arachidonate omega-hydroxylase activity; fatty acid binding; long-chain fatty acid omega-hydroxylase activity; oxidoreductase activity, acting on paired donors, with incorporation or reduction of molecular oxygen, NAD(P)H as one donor, and incorporation of one atom of oxygen; oxidoreductase activity, acting on paired donors, with incorporation or reduction of molecular oxygen, reduced flavin or flavoprotein as one donor, and incorporation of one atom of oxygen; protein binding; monooxygenase activity; heme binding; iron ion binding; medium-chain fatty acid omega-hydroxylase activity; oxidoreductase activity, acting on paired donors, with incorporation or reduction of molecular oxygen
Biological process: fatty acid metabolic process; menaquinone catabolic process; omega-hydroxylase P450 pathway; phylloquinone catabolic process; vitamin K catabolic process; arachidonate metabolic process; blood coagulation; cytochrome metabolic process; oxylipin biosynthetic process
Cellular component: endoplasmic reticulum membrane
Genetic constraint (gnomAD): Loss-of-function variants: 77 observed, 63.34 expected, observed/expected ratio (o/e) 1.22, 90% interval 1.01 to 1.47. The upper end of that interval is the gene's LOEUF score, 1.47, which puts it in group 6 of 6, group 1 being the genes least tolerant of losing a copy. Missense variants: 763 observed, 697.8 expected, observed/expected ratio (o/e) 1.09, 90% interval 1.03 to 1.16. Synonymous variants: 285 observed, 273.77 expected, observed/expected ratio (o/e) 1.04, 90% interval 0.94 to 1.15.
Homologues: Orthologues: chimpanzee CYP4F11 (99% identical), macaque CYP4F11 (91% identical), tropical clawed frog cyp4b1.5 (45% identical), rat Cyp4a1 (44% identical), mouse Cyp4a32 (44% identical), mouse Cyp4a10 (44% identical), tropical clawed frog cyp4b1.2 (44% identical), rat Cyp4a3 (43% identical), tropical clawed frog XB5810926 (43% identical), mouse Cyp4a31 (42% identical), mouse Cyp4a30b (40% identical), zebrafish cyp4t8 (38% identical), and 30 more. Paralogues in human: CYP4F2 (86% identical), CYP4F12 (83% identical), CYP4F3 (82% identical), CYP4F8 (79% identical), CYP4F22 (63% identical), CYP4A11 (44% identical), CYP4A22 (43% identical), CYP4B1 (42% identical), CYP4X1 (40% identical), CYP4Z1 (37% identical), CYP4V2 (33% identical), CYP19A1 (23% identical).
Diseases named in the same sentence as CYP4F11 in open-access papers:
CYP4F11 is named in the same sentence as 8 diseases in open-access papers, as found by Europe PMC text mining. Sharing a sentence is not in itself a finding about the gene and the disease. The quoted sentences say what the papers report.
breast carcinoma (2 papers, 2024 to 2025). "As already described for CYP4F2, both CYP4F2 and CYP4F11 are associated with ER+ breast cancer and are regulated by estrogen." (PMID 40858268, 2025). "Recently, a link between CYP4F2 and CYP4F11 expression and the progression of estrogen receptor-positive (ER+) breast cancer was established." (PMID 40858268, 2025). "As observed for CYP4F2, the genetic ablation of CYP4F11 led to a decreased proliferation of a breast cancer cell line with reduced reduction of 20-HETE." (PMID 40858268, 2025). "Compared to adjacent tissues, CYP4F11 overexpression was detected in tumor tissues of Mexican women with breast cancer." (PMID 37865919, 2024).
lung carcinoma (2 papers, 2019 to 2025). "A genetic knockout of CYP4F11 in lung cancer cell lines attenuated the cancer cell colony formation suggesting that CYP4F11 plays a role in NRF2-dependent lung cancer progression." (PMID 40858268, 2025). "Recently, the high abundance of CYP4F11 in lung cancer tumours made it an attractive tool for prodrug activation targeting the stearoyl CoA desaturase (SCD)." (PMID 40858268, 2025).
malaria (2 papers, 2023 to 2026). Malaria is a serious and sometimes fatal disease caused by a parasite that commonly infects a certain type of mosquito which feeds on humans. "The conjugation of CYP4F11 enzyme by 4-HNE, raised due to excessive lipid peroxidation in human monocytes in malaria, leads to CYP4F11 inhibition and affects hydroxylated fatty acid metabolism." (PMID 37373382, 2023). "Human cytochrome CYP4F11, involved in lipid metabolism and xenobiotic degradation, was previously shown to be inhibited by 4-HNE in a malaria model, where hemozoin-induced 4-HNE formation occurs in monocytes." (PMID 41619286, 2026). "The inhibition of CYP4F11 by 4-HNE with consequent accumulation of 15-HETE is supposed to be a crucial step in immune suppression in monocytes and immune imbalance in malaria." (PMID 37373382, 2023). "The inactivation of CYP4F11 by 4-HNE conjugation under inflammatory conditions and malaria with consequent delayed HETE degradation might offer a mechanistic explanation for the persistent inhibition of immune functions in HZ-fed monocytes and modulation of cellular immunity in malaria." (PMID 37373382, 2023).
colorectal cancer (1 paper, 2022). A primary or metastatic malignant neoplasm that affects the colon or rectum. "CYP4F11, one of omega FA metabolizing enzymes, can metabolize the compounds into irreversible inhibitors of stearoyl CoA desaturase, and its expression level is predominantly and independently associated with the OS in colorectal cancer." (PMID 35432381, 2022).
non-small cell lung carcinoma (1 paper, 2024). A group of at least three distinct histological types of lung cancer, including non-small cell squamous cell carcinoma, adenocarcinoma, and large cell carcinoma. "Rs1064796 in CYP4F11 is associated with adverse drug reactions in advanced non-small cell lung cancer." (PMID 37865919, 2024).
cancer (5 papers, 2017 to 2025). A tumor composed of atypical neoplastic, often pleomorphic cells that invade other tissues. "Since SCD has been identified as a powerful therapeutic target in cancer, the CYP4F11-mediated prodrug activation provides a strategy to inhibit SCD locally with reduced side effects." (PMID 40858268, 2025). "CATG00000038715 is near CYP4F2 and CYP4F11, encoding members of the cytochrome P450 enzyme superfamily, and the expression levels of CATG00000038715 and CYP4F2 are most highly correlated in PCa (R = 0.91, p < 2.2e-16) suggesting specificity for this cancer type." (PMID 34311724, 2021).
tumor (3 papers, 2022 to 2025). "The study evaluated both overexpression and knockout of CYP4F2 and CYP4F11 and their effects on cell proliferation, apoptosis and tumour growth." (PMID 40858268, 2025).
CYP4F11 also shares sentences with these, for which no sentence is quoted: Allergy (1 paper).